EGFR (epidermal growth factor receptor)
Diseases named in the same sentence as EGFR in open-access papers (continued):
Sharing a sentence is not in itself a finding about the gene and the disease.
adenocarcinoma (continued). "Patients of Asian ethnicity, females, never-smokers, or those with adenocarcinoma histology, were initially identified as a population with the most substantial clinical benefit from EGFR-TKIs." (PMID 25157335, 2014). "In 27 adenocarcinomas of never smokers, only three genes, EGFR, TBL3 and HSD17B7P2, occurred in two or more samples." (PMID 24894543, 2014). "However, most patients who received EGFR-TKI in this study were female (72.7%) and had adenocarcinoma (81.8%)." (PMID 24884773, 2014). "In summary, our meta-analysis demonstrated that the incidence of the EML4-ALK fusion gene was significantly higher in never or light smokers, women, patients with EGFR wild type and adenocarcinomas." (PMID 25360721, 2014). "Our data also clearly indicated that EGFR mutations are more likely to occur in TTF-1 positive tumors (145/675; 17.7%) than in TTF-1 negative adenocarcinomas (3/218; 1.4%)." (PMID 23934203, 2013). "Both EGFR gene mutations and homozygous SNP alleles (–617A/A) in the NRF2 gene were frequently observed in Japanese female adenocarcinoma patients without smoking experience." (PMID 24040073, 2013). "In the univariate analysis, women, younger patients (<65 years), never smokers, and patients with adenocarcinoma, relapsed disease after curative operation, KRAS wild type tumors, and EGFR mutation tumors were associated with longer survival." (PMID 23724098, 2013). "In unselected patients with NSCLC the prevalence of ALK positivity range from 1% to 7%, but more than 30% in patients selected for EGFR Wild-Type (WT), adenocarcinoma and no smoking history." (PMID 23359795, 2013). "ALK-positivity rates in the present study, 2.8% in the whole population and 5.1% in the group of EGFR and KRAS mutation-negative adenocarcinomas are consistent with those obtained in the many previous studies." (PMID 23936355, 2013). "Specifically, EGFR-mutated adenocarcinomas are more common in individuals who have never smoked, while KRAS-mutated adenocarcinomas occur more frequently among heavy smokers." (PMID 24179496, 2013). "EGFR mutant patients had also a predominantly adenocarcinoma histology (100%) and were predominantly never smokers (71%) but with a clear gender predisposition for females (77%)." (PMID 23359795, 2013). "It should be noted that no EGFR mutations were detected in patients with NSCLC-NOS histology, perhaps owing to a lack of adenocarcinoma patients in this group." (PMID 23892415, 2013). "EGFR testing was more commonly requested for women, younger patients, stage IV disease, non-smokers, and adenocarcinoma histology." (PMID 23468851, 2013). "In 158 EGFR and KRAS mutation-negative adenocarcinomas, 8 cases (5.1%) with iScore 3 and 150 cases with iScore 0 were identified." (PMID 23936355, 2013). "In summary, we confirm that EGFR exon mutations are frequent in patients with NSCLC, especially among females, non-smokers, and adenocarcinoma patients." (PMID 23341890, 2013). "Previous studies have demonstrated various EGFR mutations in NSCLC, including adenocarcinomas and nonadenocarcinomas." (PMID 24351833, 2013). "This diagnostic algorithm was validated in 158 patients with EGFR and KRAS mutation-negative adenocarcinoma." (PMID 23936355, 2013). "This differs from recent guidelines in Switzerland and France (French National Cancer Institute; INCa) proposing ALK testing only by FISH and only in EGFR-negative KRAS-negative adenocarcinoma patients." (PMID 22825000, 2012). "While no data on EGFR mutations were available in the present series, over-expression of ERBB3 was more common in females with adenocarcinoma, supporting, thus, results of the Japanese study." (PMID 22848476, 2012). "The response to EGFR TKIs was initially thought to be related to the clinical characterization of patients, such as Asian female non-smokers with adenocarcinomas." (PMID 23109866, 2012).
adenocarcinoma (continued). "Clinical and pathological features associated with high-frequency mutations in the EGFR tyrosine kinase (TK) domain in NSCLC include East Asian ethnicity, females, light/never smokers, and tumors with adenocarcinoma histology." (PMID 22263108, 2012). "With regard to the therapy decision, one has to bear in mind that this is not exclusively achieved by molecular-based analysis as for EGFR mutations, but also deeply depends upon the previous diagnosis of NSCLC and subdifferentiation into adenocarcinomas." (PMID 21811254, 2011). "The patients who have shown a good response to EGFR TKIs have been mainly from particular groups, including female, adenocarcinoma histology, non-smokers and Asian ethnicity." (PMID 21858063, 2011). "Somatic mutations in the EGFR gene are most frequently detected in NSCLC patients with a better outcome, including adenocarcinomas histology, in particular BAC, nonsmokers, females, and Asian ethnicity." (PMID 20672050, 2010). "CNGs were relatively frequent for EGFR and KRAS in adenocarcinomas." (PMID 19238210, 2009). "I therefore believe that KRAS and EGFR testing should be available in adenocarcinoma patients, because “adenocarcinoma” is not a unitary entity." (PMID 19672420, 2009). "Of tumors with EGFR or HER2 mutation, 72% were adenocarcinomas, 68% were from never smokers, and 32% were from former smokers." (PMID 19159467, 2009). "Therefore, EGFR mutation screening may have a higher impact on the selection of responders to gefitinib treatment among these kinds of Asian patient subset (for example, smokers with adenocarcinoma, and nonsmoking men or women with nonadenocarcinoma)." (PMID 18283321, 2008). "In all the adenocarcinoma lines, the phosphorylation state of EGFR was predictive of Akt phosphorylation without ligands stimulation." (PMID 17150102, 2006). "Thus, EGFR mutations may play a role in the aetiology of adenocarcinoma in nonsmokers." (PMID 16052218, 2005). "All the responses were reported in adenocarcinoma (two females) in which the EGFR expression was not available because the diagnosis was performed with a CT-guided fine-needle ago biopsy." (PMID 14612886, 2003). "Neither EGFR protein nor EGFR mRNA was detected in more advanced lesions such as acinar adenocarcinomas (in situ)." (PMID 8679465, 1996). "The matched group consists of 13 cases, including patients with LUAD-like subtypes who received adenocarcinoma-targeted treatments (EGFR-TKI/ Bevacizumab plus chemotherapy), and those with Non-LUAD-like subtypes who underwent SCLC-specific therapy (Chemotherapy for SCLC)." (PMID 40437627, 2025). "Similarly, female non-smokers with adenocarcinoma and EGFR-TK positivity accounted for 70%, with the majority exhibiting Exon 19 deletion." (PMID 39429333, 2024). "It has also been shown that female sex, never having smoked, Asian ethnicity and adenocarcinoma histology could be predictors of a better response to epidermal growth factor receptor (EGFR) tyrosine kinase inhibitor (TKIs) therapy." (PMID 39727929, 2024). "On the other hand, the frequency of epidermal growth factor receptor (EGFR) mutations, ALK, and ROS1 translocations are usually lower or even negative compared with other subtypes of adenocarcinomas, thus rendering them ineligible for tyrosine kinase, so their response to chemotherapy is modest." (PMID 39125981, 2024). "Notably, our study included a 35-year-old never-smoker with EGFR-positive adenocarcinoma, suggesting a possible genetic basis for the disease." (PMID 39429333, 2024). "Interestingly, EGFR and KRAS mutations appear to be more prevalent not only in adenocarcinoma, but also in Asian patients, women, and nonsmokers." (PMID 38750337, 2024). "This may also reflect our timeline, since guidelines did not recommend EGFR testing for all patients with adenocarcinoma until 2012." (PMID 38539553, 2024).
adenocarcinoma (continued). "They indeed confirmed this hypothesis by studying the effects of P38 pharmacological inhibition on cell growth in the EGFR mutant (delE746_A750) adenocarcinoma cell line (HCC827), which is derived from never smokers that do not harbour the KRAS mutation." (PMID 37686122, 2023). "Epidermal growth factor receptor (EGFR) is a common driver gene in NSCLC, and approximately 20% of NSCLC patients have activating mutations in EGFR, particularly those who have an adenocarcinoma histology and have never smoked or have a history of light smoking." (PMID 37754531, 2023). "In addition, adenocarcinoma showing micropapillary component, especially without EGFR/ALK aberration, should be first considered for BRAF testing, including immunohistochemistry." (PMID 37374289, 2023). "The seven (11.3%) samples with false-negative cobas EGFR results were all adenocarcinoma." (PMID 35945330, 2022). "Although systematic studies concerning the latency between the start of treatment and the phenotype switch in EGFR-mutant adenocarcinoma are lacking, in the large series of cases studied by Ferrer and Marcoux the median time to transformation was 16 months and 17.8 months, respectively." (PMID 35456982, 2022). "In a case report, a 76-year-old male with stage IV adenocarcinoma (cT2bN2M1b) without targetable genomic alterations, such as epidermal growth factor receptor (EGFR), anaplastic lymphoma kinase (ALK), rearranged c-ros oncogene 1 (ROS1), was diagnosed by right abdominal muscle surgical resection." (PMID 34956221, 2021). "Biopsy of the right supraclavicular lymph node revealed lung tissue adenocarcinoma and negative Kirsten rat sarcoma viral oncogene homolog (K-Ras), epidermal growth factor receptor (EGFR), B-raf proto-oncogene (BRAF), C-ros oncogene 1 (ROS1), and anaplastic lymphoma kinase (ALK) rearrangement." (PMID 33728131, 2021). "Interestingly, none of the NSCLC adenocarcinoma patients in these studies were treated with EGFR-TKIs." (PMID 34267282, 2021). "It successfully stratified EGFR wild type and low expression of PD‐L1 squamous and adenocarcinoma NSCLC (double‐negative LUAD and LUSC) patients into the high‐ and low‐risk groups, whose accuracy was proved by the time‐dependent receiver operating characteristic (ROC) curve." (PMID 34250747, 2021). "A study was performed with a customized NGS panel (called SiRe) including six genes [EGFR, KRAS, NRAS (NRAS Proto-Oncogene, GTPase), BRAF, KIT Proto-Oncogene Receptor Tyrosine Kinase (KIT)), Platelet-Derived Growth Factor Receptor Alpha (PDGFRA)] for 194 patients with advanced adenocarcinomas." (PMID 33922637, 2021). "However, among the adenocarcinoma subtype, neither EGFR nor ALK alteration impacts the outcome of this combination." (PMID 33996532, 2021). "Furthermore, useful data on EGFR‐, KRAS‐, ALK‐ and ROS‐mutational status of the adenocarcinoma subcohort is not present and fresh frozen tissue is no more attainable." (PMID 31760702, 2020). "We observed that sex, smoking, LUAD, and adenocarcinoma tissue (T) classification significantly differed between EGFR-negative and -positive patients (female vs. male: 84.2% vs. 46.8%, p < 0.001; smoking: 74.3% vs. 31.0%, p < 0.001; LUAD: 46.7% vs. 97.9%, p < 0.001; T classification: p = 0.003)." (PMID 33261184, 2020). "Our study revealed that in stage IV adenocarcinoma, the median overall survival was 34.6 months in EGFRm-positive patients who were treated with EGFR-TKIs, 12.8 months in non-EGFRm-positive patients, and 8.0 months (data not shown) in patients who were not subjected to a molecular test." (PMID 33084767, 2020). "Interestingly, EGFR L858R point mutation did not trigger higher antibody response as compared to EGFR wild type adenocarcinoma patients, nor healthy group." (PMID 31722672, 2019).
adenocarcinoma (continued). "Adenocarcinoma [sub-distribution hazard ratio (SHR) 2.40, 95% confidence interval (CI) 1.11–5.19,P = 0.027], poor performance status (SHR 1.91, 95% CI 1.18–3.09, P = 0.008), and EGFR wild-type (SHR 1.81, 95% CI 1.07–3.07, P = 0.028) were associated with an increased risk of VTE." (PMID 29743116, 2018). "Additionally, PFS was longer in the following: adenocarcinoma versus non-adenocarcinoma; TKI-sensitive versus TKI-insensitive EGFR mutations." (PMID 29402243, 2018). "Our study suggested that solid-predominant tumors had the highest expression of Mean/MWV among the various histologic subtypes, but the number of genomic triple negative adenocarcinoma was not significantly higher than that of adenocarcinoma harboring exclusive gene of either EGFR, KRAS, or ALK." (PMID 29535840, 2018). "EGFR mutated NSCLC is a molecularly defined tumor subtype (~15-20% of adenocarcinomas of the lung) with peculiar clinic-pathological features: Asian ethnicity, female sex, adenocarcinoma histology and never smoking status." (PMID 28060728, 2017). "In adenocarcinoma, 10.6% of patients (50.3% if including KRAS) could potentially be eligible for emerging therapeutics, in addition to the 15.3% of patients eligible for standard EGFR or ALK inhibitors." (PMID 28415793, 2017). "In adenocarcinoma, this analysis suggested that 10.6% (50.3% if including KRAS) of cases could be eligible for emerging targeted treatments, beyond the 15.3% of cases eligible for standard EGFR or ALK targeted therapy." (PMID 28415793, 2017). "In summary, our real‐world study showed that patients harboring EML4‐ALK rearrangement tended to be younger at diagnosis, and more of them were nonsmokers and pathological diagnosed with adenocarcinoma compared with those without ALK rearrangement and EGFR mutation." (PMID 28374971, 2017). "Molecular analyses to detect epidermal growth factor receptor (EGFR) mutations and anaplastic lymphoma kinase (ALK) rearrangement identify specific subgroups of patients, often younger and non-smokers compared to other forms of adenocarcinoma." (PMID 28560038, 2017). "EGFR TKI-sensitive mutations commonly occur in female, non-smoking and adenocarcinoma patients." (PMID 27992557, 2016). "Due to the low frequency of elevated SCCA in EGFR-mutant adenocarcinoma patients, we could not analyze its prognostic value." (PMID 27072585, 2016). "In contrast to these previous studies, the frequency of EGFR-mutant tumors in this study was assessed among patients selected on the basis of clinico-pathologic characteristics (e.g., patients with adenocarcinomas and/or non-smokers were more likely to have an EGFR test)." (PMID 27294665, 2016). "EGFR mutations were more frequently observed to be significant by multivariate analysis in NSCLC patients who were 65 years old or younger (OR = 2.51), had a nonsmoking history (OR = 3.63), and adenocarcinoma (OR = 3.57), but not in females (OR = 0.64)." (PMID 26081767, 2015). "Additionally, all lesions with adenocarcinoma histology harboured an EGFR T790M mutation, while none of the SCLC components possessed this secondary mutation in the EGFR gene." (PMID 26400668, 2015). "Conversely, let-7g was dramatically downregulated in EGFR/KRAS negative adenocarcinomas." (PMID 26273639, 2015). "In previous studies, researchers have demonstrated that activation of the EGFR pathway induced PD-L1 expression, and found PD-L1 was significantly higher in patients with the following characteristics: women, never smokers and with adenocarcinoma." (PMID 25895031, 2015). "Never-smoker East Asian females have a tendency to develop adenocarcinoma, and these never-smokers exhibit higher treatment response rates to epidermal growth factor receptor tyrosine kinase inhibitors (EGFR-TKIs), such as gefitinib and erlotinib, than those with a history of tobacco smoking." (PMID 25760072, 2015).
adenocarcinoma (continued). "Additionally, lesions with SCLC transformation may occupy a main part of the EGFR-TKI-refractory metastatic lesions, probably because of aggressiveness of SCLC compared with adenocarcinoma." (PMID 26400668, 2015). "This randomized phase II study was designed to evaluate the effect of intercalation therapy with gefitinib and paclitaxel/carboplatin chemotherapy as first-line treatment in a clinically selected population, excluding non-smoking patients with adenocarcinoma or patients with wild-type EGFR." (PMID 26493267, 2015). "Among patients with adenocarcinoma, the chemotherapy regimen and radiation dose were not different between mutant-EGFR and wild-type/unknown EGFR." (PMID 26720170, 2015). "A fraction of the adenocarcinomas also showed over expression of EGFR (Data not shown)." (PMID 25162504, 2014). "In addition, if it is needed, narrowing -down to patients with EGFR and KRAS mutation-negative adenocarcinomas seems rational, resulting in minimal risk for an inappropriate exclusion of potentially positive patients." (PMID 23936355, 2013). "Subgroups analysis according to clinical features as female sex, adonocarcinoma, non-smoker, smoker and stable disease to previous induction chemotherapy conferred OS benefit by EGFR TKIs maintenance, while patients who were male, non-adenocarcinoma, and responded to chemotherapy did not." (PMID 23555654, 2013). "It was however recognized that responses to EGFR TKIs, which were often dramatic and durable, more frequently occurred in certain populations namely females, non-smokers, patients of East Asian and those with adenocarcinoma histology." (PMID 25562798, 2012). "Importantly, although EGFR and ALK mutations are found mostly in patients with history of no smoking or light smoking who have adenocarcinoma, genotyping should be offered to all patients with advanced NSCLC if treatment with specific TKIs is available." (PMID 21444946, 2011). "None of the adenocarcinomas showed detectable EGFR amplification." (PMID 21730982, 2011). "In the present study we used A549 adenocarcinoma or NIH-3T3 cells stably over-expressing either the wild type or the L858R EGFR MT and several biochemical techniques to provide new insight into the mechanism of Tyr-phosphorylation/activation of EGFR under ox-stress." (PMID 21853092, 2011). "Interestingly, in these trials of EGFR inhibitors, EGFR expression levels in the tumors were not correlated with the response; high response rates were seen in women, patients with adenocarcinoma, nonsmokers, and Japanese patients." (PMID 15696203, 2005). "In addition, it was 2.3% among 129 adenocarcinomas without EGFR/ALK aberrations." (PMID 37374289, 2023). "The different frequency of EGFR and ALK subtypes between TTF-1 positive and TTF-1 negative subtypes might be linked to the fact that TTF-1 negative tumors in biopsies represent a group enriched in rare adenocarcinomas subtypes." (PMID 35885495, 2022). "Therefore, the relatively high expression of EGFR mutations in patients with L-PLADC can be explained by the following: the majority of patients were female and non-smokers; most patients were with adenocarcinoma and had acinar, papillary, and lepidic growth pattern." (PMID 34787725, 2021). "Therefore, EGFR mutation testing is essential and should be performed for patients with advanced non-squamous NSCLC, irrespective of the clinicopathologic features or when an adenocarcinoma component cannot be excluded." (PMID 33652831, 2021). "Adenocarcinoma to SCC lineage transformation is the least common type of acquired resistance to EGFR TKIs, although the incidence of SCC transformation during first-line osimertinib therapy might be higher than previously seen with later-line osimertinib or earlier-generation EGFR TKIs." (PMID 34572868, 2021).